UHRF2 (ubiquitin like with PHD and ring finger domains 2)
Description:
E3 ubiquitin ligase that plays important roles in DNA methylation, histone modifications, cell cycle and DNA repair. Acts as a specific reader for 5-hydroxymethylcytosine (5hmC) and thereby recruits various substrates to these sites to ubiquitinate them. This activity also allows the maintenance of 5mC levels at specific genomic loci and regulates neuron-related gene expression (By similarity). Participates in cell cycle regulation by ubiquitinating cyclins CCND1 and CCNE1 and thereby inducing G1 arrest. Also ubiquitinates PCNP leading to its degradation by the proteasome. Plays an active role in DNA damage repair by ubiquitinating p21/CDKN1A leading to its proteasomal degradation. Also promotes DNA repair by acting as an interstrand cross-links (ICLs) sensor. Mechanistically, cooperates with UHRF1 to ensure recruitment of FANCD2 to ICLs, leading to FANCD2 monoubiquitination and subsequent activation. Contributes to UV-induced DNA damage response by physically interacting with ATR in response to irradiation, thereby promoting ATR activation.
Synonyms: NIRF; RNF107; URF2; MGC33463; TDRD23
Tractability: PROTAC: UniProt records ubiquitination sites on it; ubiquitination databases record sites on it; its protein half-life has been measured.
Gene: Protein-coding gene on chromosome 9 (6,413,151 to 6,507,056, forward strand). Ensembl gene ENSG00000147854.
Subcellular location: Nucleus; Chromosome
Subcellular location (Human Protein Atlas): Nucleoplasm; Vesicles
Pathways (Reactome):
Metabolism of proteins: SUMOylation of transcription cofactors
Gene Ontology:
Molecular function: protein binding; RNA polymerase II-specific DNA-binding transcription factor binding; SUMO transferase activity; ubiquitin protein ligase activity; ubiquitin-protein transferase activity; histone binding; histone H3K9me2/3 reader activity
Biological process: cell differentiation; protein autoubiquitination; protein ubiquitination; regulation of cell cycle; protein sumoylation; regulation of transcription by RNA polymerase II; chromatin organization
Cellular component: chromosome; nucleoplasm; nucleus; pericentric heterochromatin; heterochromatin
Genetic constraint (gnomAD): Loss-of-function variants: 18 observed, 83.19 expected, observed/expected ratio (o/e) 0.22, 90% interval 0.15 to 0.32. The upper end of that interval is the gene's LOEUF score, 0.32, which puts it in group 1 of 6, group 1 being the genes least tolerant of losing a copy. Missense variants: 635 observed, 952.47 expected, observed/expected ratio (o/e) 0.67, 90% interval 0.62 to 0.71. Synonymous variants: 367 observed, 324 expected, observed/expected ratio (o/e) 1.13, 90% interval 1.04 to 1.24.
Homologues: Orthologues: chimpanzee UHRF2 (99% identical), macaque UHRF2 (99% identical), guinea pig UHRF2 (92% identical), dog UHRF2 (92% identical), pig UHRF2 (91% identical), mouse Uhrf2 (91% identical), rat Uhrf2 (90% identical), tropical clawed frog uhrf2 (67% identical). Paralogues in human: UHRF1 (55% identical), SHISA5 (8% identical).
Diseases named in the same sentence as UHRF2 in open-access papers:
UHRF2 is named in the same sentence as 52 diseases in open-access papers, as found by Europe PMC text mining. Sharing a sentence is not in itself a finding about the gene and the disease. The quoted sentences say what the papers report.
breast carcinoma (6 papers, 2015 to 2024). "Elevated expression of UHRF2 has been found in intrahepatic cholangiocarcinoma, colon cancer, breast cancer." (PMID 31245293, 2019). "Loss of function of UHRF2 decreased breast cancer cell proliferation while forced overexpression of UHRF2 gene into non-tumorigenic MCF10A breast cells induced cell proliferation." (PMID 31245293, 2019). "Consequently, alternative splicing might curb UHRF2 oncogenic roles in breast cancer through the generation of a truncated protein." (PMID 38539439, 2024). "Furthermore, while knockdown of either UHRF1 or UHRF2 led to increased DNMT3A, a more pronounced increase of DNMT3A was observed when both UHRF1 and UHRF2 were knocked down in the MDA-231 breast cancer cell line, indicating that UHRF1 and UHRF2 cooperatively regulate DNMT3A." (PMID 27462454, 2016). "Ubiquitin Like with PHD and Ring Finger Domains 2 (UHRF2), is a cell cycle regulator that promotes cell proliferation and antagonizes tumor suppressor gene expression in breast cancer." (PMID 38539439, 2024). "In breast cancer the 9p24 genomic amplicon contains six genes, among which ERMP1 and IL33 are overexpressed independently of the copy number increase, while GASC1, UHRF2, KIAA1432 and C9orf123 are overexpressed only in the context of gene amplification." (PMID 27566589, 2016).
colorectal cancer (6 papers, 2016 to 2023). A primary or metastatic malignant neoplasm that affects the colon or rectum. "Uhrf2 is high expressed in colorectal cancer, and its expression was positive associated with the grade and prognosis of colorectal cancer significantly." (PMID 37576596, 2023). "UHRF2 was one of 100 “candidate cancer (CAN) genes” mutated in breast or colorectal cancer at a higher frequency than background mutation frequency." (PMID 27738314, 2016). "Increased expression of UHRF2 in esophageal squamous cell carcinoma is negatively associated with cancer progression, whereas the reverse was true in non-small cell lung cancer, colorectal cancer, gastric cancer, and intrahepatic cholangiocarcinoma." (PMID 36690646, 2023). "Recently, emerging evidence indicated that UHRF2 was involved in the tumorigenesis and progression of several human cancers, such as esophageal squamous cell carcinoma, lung cancer and colorectal cancer 10-12." (PMID 34400880, 2021). "UHRF2 has also been recovered by different research groups from diverse sleeping-beauty mutagenesis screens wherein its deletion promotes liver, colon, nervous system tumors and notably colorectal cancers with severe disease." (PMID 27738314, 2016). "To determine whether UHRF2 and UHRF1 also negatively regulate DNMT3A in human cancer cell lines, we knocked down UHRF2 or UHRF1 in cervical cancer HeLa and colorectal cancer HCT116 cells by lentiviral-mediated shRNA infection." (PMID 27462454, 2016).
gastric cancer (5 papers, 2019 to 2023). A primary or metastatic malignant neoplasm involving the stomach. "Expressions of UHRF2 are reduced in many types of human cancers, including acute myeloid leukemia, gastric cancer, pancreatic cancer, lung cancer, and head and neck cancer." (PMID 37628583, 2023). "Similarly, downregulation of proteins associated with cell adhesion (e.g., E-cadherin and ZO-1) was reported in gastric cancer (GC) cells overexpressing Ubiquitin like with PHD and ring finger domains 2 (UHRF2)." (PMID 38067168, 2023). "The following human gastric cancer cell lines—SGC7901, MKN74, N87, and MKN45—with ectopically expressed UHRF2 were subjected to proteome profiling that has revealed upregulation of many EMT-TFs in UHRF2-overexpressing cells." (PMID 31781477, 2019).
hepatocellular carcinoma (5 papers, 2017 to 2024). A malignant tumor that arises from hepatocytes. "UHRF2 expression in both cell lines was positively correlated with intracellular HBV-associated core DNA levels of hepatoma cells and HBeAg levels in cell supernatant, which indicates the replication ability of HBV." (PMID 36690646, 2023). "Overall, we conclude that UHRF2 modulates the DHX9 protein levels via the ubiquitin-proteasome pathway in HBV-negative hepatoma cells." (PMID 36690646, 2023). "Therefore, it is excluded that upregulation of UHRF2 simultaneously promotes the development of hepatocellular carcinoma independently of DHX9." (PMID 36690646, 2023). "However, the biological function, clinical significance and underly mechanisms of UHRF2 in hepatocellular carcinoma (HCC) is largely unknown." (PMID 34400880, 2021). "UHRF2 may contribute to the initiation and development of primary hepatocellular cancer by TIP60, which warrants further investigation." (PMID 27743347, 2017). "UHRF2 enhances autophagy and oncogenic traits in hepatocellular carcinoma (HCC) by interacting with PRDX1 and PARP1, suggesting its potential as a biomarker and therapeutic target for HCC." (PMID 39315094, 2024). "We collected paired hepatocellular carcinoma tissues with corresponding paracancerous tissues from 20 HBV-positive HCC patients during 2020–2021 and analyzed the levels of UHRF2 in these tissues by Western blot assay." (PMID 36690646, 2023). "We also determined the levels of UHRF2, H3K9ac, H3K14ac, TIP60 and H2AK5ac in human hepatocellular carcinoma (HCC) tissues immunohistochemically." (PMID 27743347, 2017).
lung carcinoma (4 papers, 2014 to 2023). "To examine if UHRF2 plays a role in DNA methylation, we knocked down UHRF2 in the human lung cancer cell line A549 using shRNA and examined the DNA methylation status by immunofluorescent staining using an anti-5-meC antibody." (PMID 27462454, 2016). "Significantly, although RNA-seq data indicate increased DNMT3A transcripts in lung cancers, substantially reduced levels of DNMT3A proteins were actually detected in the tumors, and the levels of DNMT3A proteins exhibited a strong inverse correlation with that of the increased UHRF1 and UHRF2." (PMID 27462454, 2016).
osteosarcoma (4 papers, 2021 to 2024). A usually aggressive malignant bone-forming mesenchymal neoplasm, predominantly affecting adolescents and young adults. "In summary, we identified two Ub/UBL genes (TRIM8 and UHRF2) that were most strongly associated with the survival of osteosarcoma patients." (PMID 38879525, 2024). "Second, our study primarily relied on bioinformatics analysis, with validation of the differential expression of TRIM8 and UHRF2 in osteosarcoma conducted at the tissue and cellular levels." (PMID 38879525, 2024). "Tripartite Motif Containing 8 (TRIM8) and Ubiquitin Like With PHD And Ring Finger Domains 2 (UHRF2) were screened as genes with prognostic value in osteosarcoma." (PMID 38879525, 2024). "In our future research, we will validate the signaling pathways of TRIM8 and UHRF2 that potentially influence the phenotype of osteosarcoma through gene interference." (PMID 38879525, 2024). "TRIM8 and UHRF2 are potential prognostic genes in osteosarcoma, and these results provide insights into the roles of these genes and their implications for patient outcomes." (PMID 38879525, 2024). "Immunohistochemical staining for TRIM8 and UHRF2 indicated that these proteins were highly expressed in osteosarcoma tissues." (PMID 38879525, 2024). "TRIM8 and UHRF2 are potential prognostic genes for osteosarcoma." (PMID 38879525, 2024). "Finally, TRIM8 and UHRF2 were identified as prognostic hub genes in osteosarcoma by LASSO regression analysis (λ = lambda.1se)." (PMID 38879525, 2024). "Moreover, the differential expression of TRIM8 and UHRF2 in the normal and osteosarcoma groups was also successfully validated in cell lines by qRT-PCR and Western blotting and in human tissues by immunohistochemistry." (PMID 38879525, 2024). "TRIM8 and UHRF2 were confirmed to be highly expressed in osteosarcoma cell lines and tissues." (PMID 38879525, 2024). "Uhrf2 binds to the promoter of the proapoptotic gene Siva in the U2OS osteosarcoma cell line." (PMID 33670299, 2021). "In addition, studies have shown that UHRF2 has prognostic value in osteosarcoma." (PMID 38879525, 2024). "Moreover, the expression of DCAF8 was markedly decreased in osteosarcoma tissues than in adjacent normal tissues, and the expression of UHRF2 and WDR53 was not significant between osteosarcoma and normal tissues." (PMID 36060009, 2022).
intrahepatic cholangiocarcinoma (3 papers, 2021 to 2023). A carcinoma that arises from the intrahepatic bile duct epithelium in any site of the intrahepatic biliary tree. "It has been reported that UHRF2 was associated with cell invasion, migration, and lymphatic metastasis of intrahepatic cholangiocarcinoma." (PMID 34671397, 2021).
colon cancer (2 papers, 2016 to 2023). "Varley and colleagues analyzed promoter methylation of each of the 100 “CAN” genes identified as mutated in breast and colon cancer and found that UHRF2 was one of only 5 genes that was methylated in both tumor types but not normal matched tissue." (PMID 27738314, 2016). "In addition, KO of Uhrf2 extended survival time by suppressing the progression of colon cancer associated with minimum Apc expression in mice." (PMID 37628583, 2023). "On the other hand, it has been reported that Uhrf2 deletion reduced progression of colon cancer with low Apc expression in mice." (PMID 37628583, 2023).
head and neck cancer (2 papers, 2016 to 2023). A primary or metastatic malignant neoplasm affecting the head and neck. "Our results indicate that UHRF2 protein levels are widely lost in human cancer, with significant protein level reductions occurring in gastric, liver, pancreatic, lymphoma, cervical, endometrial, squamous cell carcinoma, and head and neck cancers." (PMID 27738314, 2016).
non-small cell lung carcinoma (2 papers, 2021 to 2023). A group of at least three distinct histological types of lung cancer, including non-small cell squamous cell carcinoma, adenocarcinoma, and large cell carcinoma. "Another study revealed that overexpression of UHRF2 inhibited cell migration and invasion of non-small cell lung cancer and the level of UHRF2 was positively correlated with overall survival of patients." (PMID 34400880, 2021).
acute leukemia (1 paper, 2023). A clonal (malignant) hematopoietic disorder with an acute onset, affecting the bone marrow and the peripheral blood. "Some studies reported a reduced expression of UHRF2 in acute leukemia cells, but the role of UHRF2 in hematopoiesis remains unknown." (PMID 37628583, 2023).
acute myeloid leukemia (1 paper, 2023). Acute myeloid leukemia (AML) is a group of neoplasms arising from precursor cells committed to the myeloid cell-line differentiation. "However, primary cells from most acute myeloid leukemia patients showed low UHRF2 mRNA levels." (PMID 37628583, 2023). "Furthermore, pathway analysis with IPATM showed downregulation of “acute myeloid leukemia signaling”, as well as important pathways known for HSC maintenance and differentiation in Uhrf2−/− HSPCs, including “CXCR4 signaling”, “HIF-1α signaling”, and “Ephrin receptor signaling”." (PMID 37628583, 2023).
cholangiocarcinoma (1 paper, 2016). A carcinoma that arises from the intrahepatic biliary tree (intrahepatic cholangiocarcinoma) or from the junction, or adjacent to the junction, of the right and left hepatic ducts (hilar cholangiocarcinoma). "A final fraction of cholangiocarcinomas showed sharply reduced levels of UHRF2." (PMID 27738314, 2016).
colorectal tumors (1 paper, 2016). "A similar staining profile was observed by Lu and colleagues, who analyzed UHRF2 staining in a large cohort of primary colorectal tumors." (PMID 27738314, 2016).
embryonic carcinoma (1 paper, 2016). "We designed and validated the efficacy and specificity of two small interfering RNAs (siRNAs) against each of the mouse Uhrf1 and Uhrf2 using mouse P19 embryonic carcinoma cells." (PMID 27462454, 2016).
Gastric tumors (1 paper, 2016). "Gastric tumors typically arise from these epithelial cells, and in some cases these tumors retain strong UHRF2 staining that is comparable to normal tissue." (PMID 27738314, 2016). "A final subset of gastric tumors displays a significant reduction in UHRF2 staining." (PMID 27738314, 2016). "We observed that gastric tumors also often display altered localization of UHRF2 predominantly in the cytoplasm but not the nucleus." (PMID 27738314, 2016).
glioma (1 paper, 2022). A benign or malignant brain and spinal cord tumor that arises from glial cells (astrocytes, oligodendrocytes, ependymal cells).
Hepatitis (1 paper, 2023). Inflammation of the liver. "Since UHRF2 protein levels are upregulated in HBV-associated HCC as well as in HBV-positive hepatoma cells, we identified the UHRF2 substrates which may modulate the process of HBV-associated liver diseases from hepatitis to HBV-associated HCC." (PMID 36690646, 2023).
Huntington disease (1 paper, 2024). Huntington disease (HD) is a rare neurodegenerative disorder of the central nervous system characterized by unwanted choreatic movements, behavioral and psychiatric disturbances and dementia. "Furthermore, Uhrf2 has been implicated in the ubiquitination and degradation of nuclear aggregates containing polyglutamine repeats, such as seen in Huntington’s disease and related polyglutamine diseases." (PMID 38338822, 2024).
intestinal cancer (1 paper, 2023). "Uhrf2 deletion significantly reduced intestinal cancer organoid formation and reduced the number of tumor stem cells." (PMID 37576596, 2023). "Further study revealed that Uhrf2 could bind and SUMOylate TCF4, an important transcription factor downstream of the Wnt signaling pathway, thus stabilizing TCF4 expression and activating Wnt signaling, and finally Uhrf2 promoted the progression of intestinal cancer." (PMID 37576596, 2023). "Therefore, Uhrf2 was also considered as a target for the treatment of intestinal cancer." (PMID 37576596, 2023).
intestinal tumors (1 paper, 2023). "However, UHRF2 expression in undifferentiated cells has also been reported in retinal progenitor cells, the stem/progenitor compartment of intestinal tumors, and intestinal crypt cells." (PMID 37628583, 2023).
leukemia (1 paper, 2016). A malignant (clonal) hematologic disorder, involving hematopoietic stem cells and characterized by the presence of primitive or atypical myeloid or lymphoid cells in the bone marrow and the blood. "Thus, loss of UHRF2 expression can be tied to promoter hypermethylation of CpGs in a leukemia and lymphoma cell line." (PMID 27738314, 2016). "We also examined UHRF2 expression in cord blood progenitors and compared its expression to methylation status in 6 leukemia cell lines and 15 primary human leukemias." (PMID 27738314, 2016). "We examined methylation of UHRF2 in primary human leukemia cells to determine the cancer relevance of these findings." (PMID 27738314, 2016). "To determine if UHRF2 is also decreased in hematopoietic cancer cells, we analyzed UHRF2 mRNA and protein expression pattern across six different leukemia or lymphoma cell lines." (PMID 27738314, 2016). "We were unable to definitively tie methylation status of UHRF2 to its expression in human leukemia samples." (PMID 27738314, 2016). "UHRF2 expression is reduced in some leukemia cell lines, this correlates with promoter hypermethylation, and similar UHRF2 methylation profiles are seen in primary human leukemia samples." (PMID 27738314, 2016). "Finally, the UHRF2 promoter is heavily methylated in several leukemia cell lines and this correlates with reduced expression and similar methylation is also observed in human leukemia samples." (PMID 27738314, 2016).
liver cancer (1 paper, 2016). An epithelial or non-epithelial malignant neoplasm that arises from the liver. "In gastric and liver cancers, UHRF2 appears to be preferentially localized to the cytoplasm in a subset of these tumors." (PMID 27738314, 2016).